RPS18 (ribosomal protein S18)
Description:
Component of the small ribosomal subunit. The ribosome is a large ribonucleoprotein complex responsible for the synthesis of proteins in the cell.
Synonyms: Ke3; D6S218E; KE-3; HKE3; S18; uS13
Tractability: Small molecule: an approved drug acts on it; a structure with a bound ligand is known; a high-quality ligand is known. PROTAC: UniProt records ubiquitination sites on it; ubiquitination databases record sites on it; its protein half-life has been measured; a small molecule that binds it is known. Other modalities: a drug acting on it is in phase 2 or 3 trials.
Target class: Other cytosolic protein
Gene: Protein-coding gene on chromosome 6 (33,272,075 to 33,276,511, forward strand). Ensembl gene ENSG00000231500.
Subcellular location: Cytoplasm
Subcellular location (Human Protein Atlas): Cytosol
Pathways (Reactome):
Metabolism of proteins: Eukaryotic Translation Termination; Formation of a pool of free 40S subunits; Formation of the ternary complex, and subsequently, the 43S complex; GTP hydrolysis and joining of the 60S ribosomal subunit; L13a-mediated translational silencing of Ceruloplasmin expression; PELO:HBS1L and ABCE1 dissociate a ribosome on a non-stop mRNA; Peptide chain elongation; Ribosomal scanning and start codon recognition; SRP-dependent cotranslational protein targeting to membrane; Translation initiation complex formation; ZNF598 and the Ribosome-associated Quality Trigger (RQT) complex dissociate a ribosome stalled on a no-go mRNA
Disease: SARS-CoV-1 modulates host translation machinery; SARS-CoV-2 modulates host translation machinery; Viral mRNA Translation
Metabolism of RNA: Major pathway of rRNA processing in the nucleolus and cytosol; Nonsense Mediated Decay (NMD) enhanced by the Exon Junction Complex (EJC); Nonsense Mediated Decay (NMD) independent of the Exon Junction Complex (EJC)
Cellular responses to stimuli: Response of EIF2AK4 (GCN2) to amino acid deficiency
Developmental Biology: Regulation of expression of SLITs and ROBOs
Metabolism: Selenocysteine synthesis
Gene Ontology:
Molecular function: protein binding; RNA binding; structural constituent of ribosome; nucleic acid binding
Biological process: cytoplasmic translation; translation
Cellular component: cytoplasm; cytosol; cytosolic ribosome; cytosolic small ribosomal subunit; extracellular exosome; focal adhesion; membrane; nucleus; postsynaptic density; small ribosomal subunit; nucleoplasm; ribosome; synapse
Genetic constraint (gnomAD): Loss-of-function variants: 0 observed, 14.32 expected, observed/expected ratio (o/e) 0, 90% interval 0 to 0.21. The upper end of that interval is the gene's LOEUF score, 0.21, which puts it in group 1 of 6, group 1 being the genes least tolerant of losing a copy. Missense variants: 35 observed, 134.62 expected, observed/expected ratio (o/e) 0.26, 90% interval 0.2 to 0.34. Synonymous variants: 46 observed, 44.57 expected, observed/expected ratio (o/e) 1.03, 90% interval 0.81 to 1.32.
Homologues: Orthologues: chimpanzee RPS18 (100% identical), guinea pig RPS18 (100% identical), mouse Rps18 (100% identical), pig RPS18 (100% identical), rat Rps18l1 (100% identical), zebrafish rps18 (98% identical), Drosophila melanogaster RpS18 (78% identical), Caenorhabditis elegans rps-18 (76% identical), dog RPS18 (68% identical).
Diseases named in the same sentence as RPS18 in open-access papers:
RPS18 is named in the same sentence as 30 diseases in open-access papers, as found by Europe PMC text mining. Sharing a sentence is not in itself a finding about the gene and the disease. The quoted sentences say what the papers report.
Parkinson disease (3 papers, 2020 to 2025). A progressive degenerative disorder of the central nervous system characterized by loss of dopamine producing neurons in the substantia nigra and the presence of Lewy bodies in the substantia nigra and locus coeruleus. "The SAES-correlated gene CPEB4, exhibiting RNA binding activity, is within an IBD GWAS locus, and autoantibodies against ribosomal protein RPS18 are potential biomarkers for early-stage Parkinson's disease." (PMID 39165421, 2024). "Another group of authors obtained data on two new protein biomarkers of Parkinson’s disease—mitochondrial ribosome recycling factor (MRRF) and ribosomal protein S18 (RPS18), the increase of which is particularly relevant in determining the prodromal stage of Parkinson’s disease." (PMID 32466249, 2020).
Sepsis (3 papers, 2024 to 2026). Sepsis is defined as life-threatening organ dysfunction caused by a dysregulated host response to infection. "In conclusion, our study provides important data on the clinical value of Cell-free DNA, represented here by mt-ND1, mt-CO3 and n-Rps18 in patients with sepsis." (PMID 38803503, 2024). "Our analysis revealed that, at day 3, patients with sepsis had elevated levels of cfDNA (mt-ND1, and n-Rps18, all p<0.001) which decreased after the acute phase of sepsis." (PMID 38803503, 2024). "We assumed that another three cis-eQTL genes (PDK2, RPS18, and NDUFV3), which were negatively associated with sepsis-induced ARDS, could be targeted with potential drugs in ARDS treatment." (PMID 40116326, 2025). "Clinical qPCR validation confirmed that RPLP0 was significantly upregulated in sepsis patients, while CD52, RPS15A, and RPS18 were downregulated." (PMID 42291321, 2026). "We discovered potential drug targets for sepsis-related ARDS through a comprehensive analysis, among which four druggable targets (PSMA4, PDK2, RPS18, and NDUFV3) should be dialectically treated." (PMID 40116326, 2025). "Subsequent drug target analysis confirmed the role of four targets (PSMA4, PDK2, RPS18, and NDUFV3) as druggable genes for sepsis-related ARDS." (PMID 40116326, 2025).
breast carcinoma (2 papers, 2023 to 2024). "We found that the e2QTL for ARL17B upon UVC and RPS18 upon HC exposure represent GWAS risk variants for breast cancer (r2 = 0.91, r2 = 1), both exhibiting reduced expression in carriers of the risk alleles." (PMID 39623312, 2024). "In addition, context specific regulatory effects for ARL17B and RPS18 were found to be associated with breast cancer." (PMID 39623312, 2024). "RPS18 is a reference parameter in the demonstration of multiplex nucleic acid sequence-based amplification (NASBA) on microarray analysis for breast cancer diagnostics." (PMID 36984424, 2023).
fungal infection (2 papers, 2019 to 2020). "After fungal infection, RPS3, RPS18, and RPL13a expressed stably in T. castaneum." (PMID 33085726, 2020).
influenza (2 papers, 2020 to 2023). An acute viral infection of the respiratory tract, occurring in isolated cases, in epidemics, or in pandemics; it is caused by serologically different strains of viruses (influenzaviruses) designated A, B, and C, has a 3-day incubation period, and usually lasts for 3 to 10 days. "UBE2D2 and RPS18 were reported to be stable in PBMCs collected 4 weeks after influenza vaccination." (PMID 36627346, 2023). "This study suggests the use of a combination of UBE2D2, RPS18, and ACTB for the study of influenza responses in PBMCs and T-cells, although ACTB alone may be the most optimal choice if choosing to compare target gene expression before and after viral stimulation." (PMID 32005148, 2020).
prostate carcinoma (2 papers, 2010 to 2023). A carcinoma that arises from epithelial cells of the prostate gland. "Among the ribosomal proteins that we observed to be associated with our EC samples, RPS18 and RPL18A have been previously reported in association with colon cancer and RPS14 and RPS18 in prostate cancer." (PMID 37760635, 2023).
viral infection (2 papers, 2020 to 2021). "Although our study showed that rpl32 displayed stable expression in A. mellifera under dsRNA treatment, it exhibited the worst stability during IAPV and CBPV infection in A. mellifera, while rps18 was the better reference gene in A. mellifera under dsRNA treatment or viral infection." (PMID 32849362, 2020).
autism (1 paper, 2025). Persistent deficits in social interaction and communication and interaction as well as a markedly restricted repertoire of activity and interest as well as repetitive patterns of behavior. "Increased levels of RPS18 mRNA in PBMCs were associated with decreased intellectual functioning, but not autism features as assessed using ADOS-2 for children with PWS due to non-deletion (< 13 years of age)." (PMID 41444386, 2025). "Our follow-up studies in PBMCs from another cohort found that expression of RPS18 was also related to intellectual functioning and oppositional behaviors, but not autism features in PWS." (PMID 41444386, 2025).
colorectal cancer (1 paper, 2024). A primary or metastatic malignant neoplasm that affects the colon or rectum. "In the context of gastric cancer, RPL15, RPL6 and RPS13 exhibited upregulated expressions, while in colorectal cancer, RPS18, RPS23, RPL28 and RPL32 were found to be downregulated, implicating these ribosomal proteins as potential diagnostic markers for gastric and colorectal cancers, respectively." (PMID 39684863, 2024).
COVID-19 (1 paper, 2020). A disease caused by infection with severe acute respiratory syndrome coronavirus 2. "Although the analysis was limited to only two patients without individual cell-type resolution, in genome browser, up-regulation of IFITM1, ISG15, and JAK3 and down-regulation of RPS18 were observed commonly in post-mortem COVID-19 lung tissues and classical monocytes of severe COVID-19." (PMID 32651212, 2020).
esophageal cancer (1 paper, 2022). A primary or metastatic malignant neoplasm involving the esophagus. "PPIA had the most stable expression in esophageal cancer tissues (CA) and all esophageal tissues (ALL); RPS18 had the most stable expression in normal esophageal tissues (NO)." (PMID 36467891, 2022).
glioblastoma (1 paper, 2023). The most malignant astrocytic tumor (WHO grade IV). "For example, with glioblastoma, eS6 (RPS6), eS27 (RPS27), uS8 (RPS15A) and eL34 (RPL34) are known as oncogenic, whereas uL18 (RPL5), uS17 (RPS11), uS9 (RPS16) and uS13 (RPS18) are found to have a tumor-suppressive function." (PMID 37511213, 2023).
hepatocellular carcinoma (1 paper, 2025). A malignant tumor that arises from hepatocytes. "Moreover, this initiates dysfunction in patrolling neutrophils and causes further pathological conditions, such as hepatocellular carcinoma, in ALD‐induced mice by downregulating RPS18." (PMID 41190282, 2025).
ischemia (1 paper, 2025). A hypoperfusion of the BLOOD through an organ or tissue caused by a PATHOLOGIC CONSTRICTION or obstruction of its BLOOD VESSELS, or an absence of BLOOD CIRCULATION. "The expression of RPL10A, RPL14, RPL30, RPS18, FAU-40 (RPS30), and RPSA (Laminin Receptor, LR) was assessed in the myocardial and EAT tissues of MI, CABG and HL swine models and in LVSCs and EATDS challenged with ischemia." (PMID 39641799, 2025). "Importantly, the EATDS-derived exosomes have been unveiled for their potential cardiac responses and our previous findings identified major ribosomal proteins including RPL10A, RPL14, RPL30, RPS18, FAU-40 (RPS30), and RPSA (Laminin Receptor, LR) in the vesicles of ischemia-challenged EATDS." (PMID 39641799, 2025).
pancreatic adenocarcinoma (1 paper, 2024). "The main focus of this study is to explore the molecular mechanism of IRF7 regulation on RPS18 transcription in M1‐type macrophages in pancreatic adenocarcinoma (PAAD) tissue, as well as the transfer of RPS18 by IRF7 via exosomes to PAAD cells and the regulation of ILF3 expression." (PMID 39118300, 2024).
pancreatic cancer (1 paper, 2024). "The study highlights the transfer of RPS18 via exosomes from M1 macrophages to pancreatic cancer cells, affecting the expression of ILF3 and thereby influencing the cancer cells' viability, migration, proliferation and apoptosis." (PMID 39118300, 2024). "This document is a detailed study on the role of IRF7 and RPS18 in regulating pancreatic cancer progression, specifically through the interactions between M1 macrophages and pancreatic cancer cells." (PMID 39118300, 2024).
renal carcinoma (1 paper, 2021). A carcinoma arising from the epithelium of the renal parenchyma or the renal pelvis. "Most of the genes have usually been investigated as prognostic biomarkers in renal cancer, and RPS18, RPL30, NME2, and RPS25 usually have been investigated as unfavorable predictors, while GAB2 has been reported as favorable predictor in renal cancer." (PMID 34208938, 2021).
thymoma (1 paper, 2013). A neoplasm arising from the epithelial cells of the thymus. "In B3 thymomas, most of the enriched pathways concerned translation, including down-regulation of the ribosomal protein genes RPS6 and RPS18, which is rare in other cancers." (PMID 24427739, 2013).
tumor (10 papers, 2002 to 2025). "Conversely, the percentage of Ki67‐positive cells in the mouse tumour tissue encountered a rise in the oe‐IRF7‐Exos + oe‐RPS18 group contrasting with the oe‐IRF7‐Exos + oe‐NC group." (PMID 39118300, 2024). "In contrast, the growth rate of tumours in mice from the oe‐IRF7‐Exos + oe‐RPS18 group was even faster than that of the oe‐IRF7‐Exos + oe‐NC group." (PMID 39118300, 2024). "In the total lysate we observed significant enrichment of ribosomal proteins and increased tumor abundance of several structural ribosomal subunits: 6 proteins of the large ribosomal subunit, and 4 of small ribosomal subunit including top classifier Rps18." (PMID 31061415, 2019). "Nonetheless, RPS18 and ILF3 expression in tumour tissues of mice from the oe‐IRF7‐Exos + oe‐RPS18 group was elevated contrasting with the oe‐IRF7‐Exos + oe‐NC group." (PMID 39118300, 2024). "Initially, using RT‐qPCR and Western blot analysis, we observed a notable decrease in the expression of RPS18 and ILF3 in the tumour tissues of mice belonging to the oe‐IRF7‐Exos + oe‐NC group relative to the NC‐Exos + oe‐NC group." (PMID 39118300, 2024). "The ranking demonstrated that RPS18 was the most stably expressed gene in group ALL; PPIA was in a single group of normal and tumor tissue with std dev [±CP] less than 1.0." (PMID 36467891, 2022). "When a stably expressed single internal reference is used for normalization, RPS18 and PPIA, the high and low patterns of RE between normal and tumor were similar, and the trends were the same as the sequencing results." (PMID 36467891, 2022). "In tumor tissue and/or normal mucosa, the four best normalization genes are ALAS, GAPDH, RPS18 and SHAD and the most stable combination of two genes is GAPDH-SHAD." (PMID 19650912, 2009).
cancer (8 papers, 2002 to 2022). A tumor composed of atypical neoplastic, often pleomorphic cells that invade other tissues. "Some of the proteins that we identified have already been reported to be overexpressed in various types of cancer, including ribosomal protein S18, RAN binding protein 7, and eIF3, p40 subunit." (PMID 12177805, 2002). "ACTB and RPS18 displayed a high abundance in cancer and normal tissues." (PMID 36467891, 2022). "Furthermore, ribosomal proteins like the 40S ribosomal protein S18 is known to promote cancer cell growth by inhibiting P27; polyphyllin’s action on decreasing this critical entity reflects upon the inhibition of cell growth of DLD-1 cells that we observed in the cellular level analysis." (PMID 35327385, 2022). "Under the conditions of this experiment, the combinations of two suitable internal reference genes of cancer esophageal tissues, normal esophageal tissues, and all samples were PPIA and RPS18." (PMID 36467891, 2022).
bacterial infection (5 papers, 2018 to 2025). "In the context of bacterial infection, the head RPS18 and GAPDH genes of Apis mellifera L. (Hymenoptera: Apidae) are able to express stably." (PMID 40266757, 2025). "In addition, rpS18 and gapdh have been identified as optimal reference genes in the honey bee head in the context of bacterial infection." (PMID 29985960, 2018).
infection (3 papers, 2021 to 2025). The state of being infected such as from the introduction of a foreign agent such as serum, vaccine, antigenic substance or organism. "Additionally, RPS3, RPS18, and RPL13α are stably expressed in T. castaneum after infection with Beauveria bassiana." (PMID 40266757, 2025). "In addition, we validated the relative expression of some of the Rpl and Rps transcripts by RT-PCR and found the significantly lowered expression of Rpl4, Rpl12, Rps18, Rps19 during the infection compared to naïve animals." (PMID 35789215, 2022). "Research has shown that RPS18 and GAPDH are stably expressed in Apis mellifera after infection with Escherichia coli." (PMID 40266757, 2025).
RPS18 also shares sentences with these, for which no sentence is quoted: chronic myeloid leukemia (1 paper); colon cancer (1); head and neck squamous cell carcinoma (1); heart failure (1); kidney damage (1); leukemia (1); oral carcinoma (1); sunburn (1).